BRAF (B-Raf proto-oncogene, serine/threonine kinase)
Diseases named in the same sentence as BRAF in open-access papers (continued):
Sharing a sentence is not in itself a finding about the gene and the disease.
colorectal cancer (continued). "Given the presence of the BRAFV600E mutation in benign melanocytic nevi, pre-malignant colon polyps and early stage colorectal cancer, the oncogenic potential of mutated BRAF has been under investigation." (PMID 23372575, 2012). "We found that BRAF mutation increases the risk of mortality in colorectal cancer patients by more than two-fold." (PMID 23056577, 2012). "We found that BRAF-V600E mutation increases the risk of mortality in colorectal cancer patients for more than two-fold." (PMID 23056577, 2012). "KRAS mutations are seen in 40–50% of CRC, while BRAF mutations are seen in 10% of colorectal cancer." (PMID 23097702, 2012). "BRAF mutant/MSS cancers are an important subgroup of colorectal cancer due to their association with a particularly poor patient prognosis." (PMID 23110075, 2012). "Mutations of KRAS and BRAF genes are frequently found to be mutually exclusive in colorectal cancer, both in Western and Chinese patients." (PMID 22586484, 2012). "The number of reports on BRAF mutation and colorectal cancer were enough to pool the results together and perform a meta-analysis." (PMID 23056577, 2012). "In our pooled data for colorectal cancer only one paper reported a protective HR (less than one) for BRAF mutation." (PMID 23056577, 2012). "BRAF mutation has been reported to be more frequent in stage I to IV human colorectal carcinomas with a high lymphocytic infiltration." (PMID 22879926, 2012). "In summary, we observed a moderate rate of KRAS mutations (145/478; 30.3%) or PIK3CA mutations (67/384; 17.4%) and a very low rate of BRAF mutations (1/384; 0.3%) in a cohort of primary colorectal carcinomas." (PMID 22931052, 2012). "Whereas BRAF mutations are relatively more common in MSI colorectal carcinomas, for adenomas this is less straightforward." (PMID 22848674, 2012). "Microsatellite instability (MSI), a recognized marker of a tendency for replication errors in human cancers, has been widely indicated as a factor associated with higher frequency of mutations in BRAF gene among colorectal carcinomas." (PMID 22931052, 2012). "In recent meta-analyses, the BRAF V600E mutation - which represents the most common mutation in BRAF gene (more than 90% of cases) - was detected in about 9% of primary colorectal carcinomas." (PMID 22931052, 2012). "Consistent with earlier reports, our results show that KRAS and BRAF mutation frequencies in colorectal cancer were 44.3% and 13.0%, respectively, while EGFR mutations were detected in 11.1% of the lung cancer specimens." (PMID 21943394, 2011). "Although testing of greater numbers of PTEN mutant samples is required to validate these observations, these data show that MSI and PTEN mutations, in exons 7 and 8 at least, occur together in the same colorectal cancers, along with BRAF mutations." (PMID 21473780, 2011). "BRAF mutation has been found to be an independent prognostic factor for decreased survival in colorectal cancer patients on univariate as well as multivariate analysis." (PMID 24212832, 2011). "All colorectal cancers that harbored BRAF mutation as well as the vast majority (98%) of cancers with the MSI phenotype were biomarker panel positive, in line with the CIMP concept." (PMID 21777459, 2011). "As approaches to CIMP characterization in colorectal cancer continue to evolve, it is clear that BRAF and KRAS oncogene mutations will continue to refine any definition of CIMP." (PMID 21559209, 2011). "As expected, the identified methylation markers were frequently detected in MSI positive colorectal cancers containing BRAF mutations, features that are consistent with the CIMP positive phenotype." (PMID 21777459, 2011).
colorectal cancer (continued). "In colorectal cancers the incidence of KRAS or BRAF mutations are about 50% of patients (roughly 40% KRAS and 10% BRAF mutations) and was a found to be associated with poor prognosis in colorectal cancer." (PMID 24212832, 2011). "Activating mutation of KRAS and BRAF are focused on as potential prognostic and predictive biomarkers in patients with colorectal cancer (CRC) treated with anti-EGFR therapies." (PMID 21285991, 2011). "High degree of CIMP (CIMP-high) is a distinct phenotype in colorectal cancer, associated with older age, female gender, proximal tumor location, microsatellite instability, BRAF mutation, and high-level tumor LINE-1 methylation." (PMID 21738611, 2011). "Cells of the colorectal cancer line HT-29 have a mutated BRAF gene (V600E) and are relatively resistant to cytotoxicity by anti-EGFR antibody cetuximab." (PMID 20976159, 2010). "Activating mutations in both genes have been found in colorectal cancer with mutation frequencies of 4-13% for BRAF and of 20-50% for K-ras having been reported." (PMID 20233436, 2010). "None of the dietary factors tested displayed a statistically significant association with BRAF mutations in colorectal cancers." (PMID 20233436, 2010). "BRAF mutation in colorectal cancers was observed at a frequency of 15.6% and K-ras mutation at 22.0%." (PMID 20233436, 2010). "Oncogenic mutations in KRAS or BRAF occur frequently in colorectal cancer and aberrant signaling through the ERK pathway has been correlated with both initiation and progression of CRC." (PMID 20942929, 2010). "Clinicopathological and lifestyle characteristics of colorectal cancer cases by BRAF or K-ras mutation status and K-ras mutated cancers by specific K-ras mutation types." (PMID 20233436, 2010). "The data presented herein suggest that BRAF and K-ras mutations arise in an almost mutually exclusive manner in distinct subsets of colorectal cancer, that differ in terms of clinicopathological features, dietary factors and lifestyle exposures." (PMID 20233436, 2010). "This study is the first to undertake a comprehensive analysis of BRAF mutations in colorectal cancer and their relationship to dietary factors." (PMID 20233436, 2010). "This study is the most comprehensive to date examining dietary factors and BRAF mutations in colorectal cancer." (PMID 20233436, 2010). "Taken together, these data confirm that the clinicopathological signature of BRAF mutated colorectal cancer includes proximal location, microsatellite instability and poor differentiation." (PMID 20233436, 2010). "The testing presented herein demonstrates the independent clinicopathological nature of colorectal cancers with either BRAF or K-ras mutations." (PMID 20233436, 2010). "To elucidate regulatory principles of pathway-triggered gene transcription, we firstly identified common clusters of target genes sensitive to MEK inhibition in three colorectal cancer cell lines carrying KRAS or BRAF mutations." (PMID 21170361, 2010). "BRAF V600E mutation was found in 15.6% of colorectal cancers but at higher frequencies in cancers with proximal location, poor differentiation and microsatellite instability (MSI) (all p < 0.001)." (PMID 20233436, 2010). "This study investigates the associations between BRAF and K-ras mutations and clinicopathological, lifestyle and dietary factors in colorectal cancers." (PMID 20233436, 2010). "Microsatellite instability has been linked to proximal location and has been consistently linked to BRAF mutation in colorectal cancer: one review described BRAF mutation as a 'hallmark' of MSI tumours." (PMID 20233436, 2010). "These frequencies are at the high and low ends of the ranges previously reported for mutations in these genes in colorectal cancer: 4-13% for BRAF and 20-50% for K-ras." (PMID 20233436, 2010). "Activating BRAF mutations are present in 29–69% of papillary thyroid carcinomas, are also common in colorectal cancers and present in 4% of small cell lung cancers." (PMID 19724275, 2009).
colorectal cancer (continued). "We selected 21 colorectal cancer cell lines, characterized their DNA methylation profiles, and determined their BRAF and KRAS mutation status." (PMID 20027224, 2009). "The importance of Raf in oncogenic signaling has been validated by the discovery of activating BRAF mutations in a variety of human tumors, including 14% of colorectal cancers." (PMID 19014680, 2008). "Using a microsatellite stable (MSS) colorectal cancer (CRC) cell line (Colo741) having mutated BRAF and KRASWT, we also aimed to investigate the KRAS-BRAF interaction." (PMID 19087308, 2008). "In order to understand the importance of KRAS, PIK3CA and BRAF mutations for the progression of the various types of colorectal cancer, we compared the frequency of these oncogenic events in the series of polyps and in 50 MSI and 53 MSS CRC." (PMID 18782444, 2008). "The serrated pathway shown in about 15% of the colorectal carcinomas demonstrates BRAF mutation and methylation/silence of the MLH-1 mismatch repair complex in the context of microsatellite instability." (PMID 18983642, 2008). "Activating mutations in BRAF have recently been found in about 10% of colorectal cancers, with the vast majority being a V600E hotspot mutation." (PMID 16403224, 2006). "The serrated neoplasia pathway is a major molecular route to colorectal carcinogenesis, accounting for approximately 15%-30% of sporadic colorectal cancers and characterized by early BRAF V600E mutation, CpG island methylator phenotype, and distinct histopathologic features." (PMID 42200009, 2026). "Similarly, the BEACON CRC trial established the superiority of Encorafenib combined with Cetuximab over standard chemotherapy for BRAF V600E-mutated colorectal cancer." (PMID 41361128, 2025). "Similarly, almost all genes with established literature associations to BRAF were reported in thyroid cancer, despite using balanced sets of thyroid (396 samples) and colorectal cancers (112 samples) in the analysis." (PMID 40775769, 2025). "We set out to obtain clues about why some colorectal cancers grow with atypical BRAF driver mutations that are predicted to have impaired or suboptimal kinase activity and thus result in weak downstream MAPK signaling in comparison with the most frequently observed V600E class 1 variant." (PMID 39751654, 2025). "Overall, our results suggest that BRAF class 3 colorectal cancers have better survival than class 1 colorectal cancers, but the additional Ras pathway mutations in some class 3 BRAF-mutant colorectal cancers result in survival similar to that associated with class 1 V600E." (PMID 39751654, 2025). "Our data suggests a predictive role for RNF43 mutation in response to encorafenib and cetuximab and when viewed in the context of other available data, suggests the utility of routine testing of RNF43 in patients with BRAF-mutated colorectal cancer, if external validation is supportive." (PMID 41002577, 2025). "And the BRAF V600E mutation accounts for approximately 95% of BRAF-mutated colorectal cancers." (PMID 41225509, 2025). "However, actionable BRAF mutations account for only a small fraction of the genetic landscape in colorectal cancer." (PMID 40942081, 2025). "Based on previous models of “polygenic” tumorigenesis in hypermutant cancers, we wondered whether the multiple BRAF and Ras pathway mutations in class 2 and 3 BRAF-mutant colorectal cancers were driven by a mutator phenotype." (PMID 39751654, 2025). "Colorectal cancer, BRAF mutation, tertiary lymphoid structures, tumor microenvironment, prognosis." (PMID 40959083, 2025). "Dabrafenib, a BRAF inhibitor could also be considered in combination with trametinib (MEK inhibitor), as the combination has already been used in BRAF-mutated colorectal cancer patients, particularly when these drugs were first introduced." (PMID 40526090, 2025).
colorectal cancer (continued). "As little under half of BRAF class 3 colorectal cancers in our analysis carry additional pathogenic Ras pathway mutations, we speculate that the efficacy of anti-EGFR therapy in this subset of double-mutant patients may be diminished." (PMID 39751654, 2025). "Lastly, while the strong association between BRAF p.V600E mutations and colorectal cancer-specific death in female patients with rectal tumors is intriguing and may reflect underlying biological influences, the number of events in this subgroup is small." (PMID 41413856, 2025). "However, it was demonstrated that BRAFV600E degradation causes an immediate decrease in BRAF‐mediated signaling, and the same findings in the cell lines of H29 colorectal cancer were verified that are dependent on BRAF." (PMID 39898116, 2025). "However, the mutation rates of KRAS and BRAF in colorectal cancer patients are only 40% and 10%, respectively." (PMID 40547026, 2025). "In Genomics England 100,000 Genomes Project colorectal cancers with either a class 2 or 3 BRAF variant and an additional Ras pathway variant, we investigated whether these mutations were present in different cancer subclones or in the same cell." (PMID 39751654, 2025). "Additionally, in more challenging BRAF-mutated colorectal cancers, a combinatorial therapy of Alpelisib, Encorafenib, and Cetuximab has shown to be effective as well." (PMID 40943615, 2025). "Firstly, we incorporated the most recent data covering new and updated information (to May 2025), enabling comprehensive evaluation of both first line and subsequent line targeted therapies in BRAF-mutated colorectal cancer." (PMID 41355781, 2025). "Therefore, investigating the impact of the BRAF V600E mutation on immunotherapy in colorectal cancer is crucial." (PMID 39934467, 2025). "BRAF mutations are prevalent in colorectal cancer (CRC) and generally confer a poor prognosis." (PMID 40959083, 2025). "In addition to KRAS, mutations in BRAF also play an important role in colorectal cancer, although they are less common compared to KRAS mutations." (PMID 40083375, 2025). "We found that BRAF V600E mutation has a complex impact on the immune profile of colorectal cancer." (PMID 39934467, 2025). "Machine learning using Elastic-net allowed us to build a mixed metabolism/mitochondrial activity score, which was found to be increased in the CMS1-MSI subtype and metastatic samples and to be an independent parameter predictive of BRAF-V600E mutation status in colorectal cancer." (PMID 41440935, 2025). "After excluding patients with unknown mismatch repair (MMR) status (n=39) or unknown RAS or BRAF mutational status (n=72), 2236 colorectal cancer (CRC) patients were available for analyses." (PMID 40340947, 2025). "Furthermore, when GLI1 blockers were tested in laboratory models of BRAF-mutated colorectal cancer, they yielded promising results in reducing tumor growth by suppressing the NBS1 levels in BRAF-mutated cancers." (PMID 39851545, 2025). "Additionally, five cases exhibited both MLH1 promoter hypermethylation and a BRAF V600E mutation—findings typically associated with sporadic MSI-H colorectal cancers." (PMID 40806271, 2025). "In this study, we use 13 colorectal cancer cohorts with genome, exome, or panel sequencing data to investigate the mutational landscape of colorectal cancers with class 2 or 3 BRAF mutations." (PMID 39751654, 2025). "Secondly, the “Incidence - SEER Research Data, 8 Registries, Nov 2023 Sub (1975–2021)” package lacks data on molecular biomarkers such as microsatellite instability/mismatch repair and RAS/BRAF mutations, which are considered valuable in colorectal cancer prognosis." (PMID 40597951, 2025). "Targeted therapy based combinations are critical for advanced BRAF-mutated colorectal cancer." (PMID 41355781, 2025).
colorectal cancer (continued). "Targeted therapy for BRAF-mutated colorectal cancer has evolved from conventional anti-VEGF/anti-EGFR based regimens to BRAF targeted therapy; however, none achieved substantial clinical benefits until the BEACON trial established the efficacy of dual EGFR/BRAF inhibition." (PMID 41355781, 2025). "Background/Objectives: The BRAF-mutation is a poor prognostic factor in colorectal cancer (CRC)." (PMID 40149341, 2025). "Given that mutations in APC, KRAS, and BRAF are among the most frequently occurring genetic alterations in colorectal cancer, our findings suggest that the Prkci–c-Myc axis may represent a generalizable and mutation-independent oncogenic mechanism in CRC." (PMID 41188443, 2025). "BRAF V600E mutation-positive advanced recurrent colorectal cancer has a poor prognosis." (PMID 38741697, 2024). "Mutated genes common to both lung and colorectal cancers include BRAF and KRAS." (PMID 38770671, 2024). "THRAP3 was reported to be a tumor suppressor in BRAF-mutated colorectal cancer." (PMID 38333620, 2024). "In addition, B-Raf proto-oncogene (BRAF) is frequently mutated in melanoma, thyroid cancer, colorectal cancer, and ovarian cancer." (PMID 38672455, 2024). "By adding microsatellite status and primary tumor site on the basis of pathological stage, we improved the discriminability and prediction accuracy of the model and successfully established a prognosis model for patients with BRAF V600E mutation of colorectal cancer." (PMID 39464719, 2024). "BRAF K601E mutations were also more frequent in colorectal cancers in Black patients." (PMID 38297963, 2024). "Additionally, the presence of BRAF mutations in colorectal cancer (CRC) is associated with a higher likelihood of metastatic disease, indicating the aggressive nature of this cancer subtype." (PMID 39768914, 2024). "ABCA3 expression is associated with poor survival and multidrug resistance in Leukemia cells and may have similar functions in BRAF-mutated colorectal cancer." (PMID 38982444, 2024). "MTX-211 (also known as Mol 211, HY-107364), functioning as a dual inhibitor targeting both epidermal growth factor receptor (EGFR) and phosphoinositide-3 kinase (PI3K), exhibited potent in vivo growth-inhibitory effects against colorectal cancer models characterized by BRAF and KRAS mutations." (PMID 38791198, 2024). "Can CT-based radiomics signature predict KRAS/NRAS/BRAF mutations in colorectal cancer?" (PMID 38608072, 2024). "Previous reports have shown that almost all colorectal cancers with BRAF mutation are classified as HMCC; therefore, the inclusion of patients with BRAF mutation may have contributed to the poor clinical outcomes observed in the HMCC group." (PMID 38862615, 2024). "Late-onset colorectal cancer (occurring in those 80 years of age or older) compared to earlier onset is more likely to be right-sided (82% vs. 35%) and dMMR (35% vs. 8%)—particularly driven by the BRAF V600E mutation (35% vs. 8%)." (PMID 38791899, 2024). "Colorectal carcinomas with BRAF mutations show higher expression of PD-L1, which can contribute to immune evasion of cancer cells and in turn nuclear PD-L1 promotes cell cycle progression of BRAF mutant cells." (PMID 38774235, 2024). "The low frequency of APC and BRAF mutation in our series is in keeping with the findings of others and supports the concept that these genes are mutated rarely in pseudomyxoma peritonei, in contrast to colorectal carcinomas." (PMID 39435876, 2024).